ALB (albumin)
Diseases named in the same sentence as ALB in open-access papers (continued):
Sharing a sentence is not in itself a finding about the gene and the disease.
Hypoalbuminemia (continued). "Second, we used plasma albumin concentration, instead of surfactant level, to estimate changes in KpELF; while this may not be ideal, we consider it a reasonable surrogate marker since hypoalbuminemia has been found to be linked to infection severity." (PMID 40323339, 2025). "However, AG is susceptible to the concentration of ALB, and in cases of hypoalbuminemia, AG may be underestimated." (PMID 40844993, 2025). "Hypoalbuminemia, particularly low levels of albumin, affects plasma colloid osmotic pressure, which may cause tissue edema and increase cardiac burden, and is associated with a chronic inflammatory state, affecting heart structure and function, thus increasing the risk of myocardial ischemia." (PMID 40703271, 2025). "Although hypoalbuminemia and low vitamin D status are recognised risk factors for postoperative wound complications, they cannot account for the excess observed in the suicidal group, as cohort albumin (p = 0.730) and vitamin D (p = 0.740) levels were comparable." (PMID 41288725, 2025). "Likewise, a Japanese longitudinal study of 600 community-dwelling adults aged ≥ 70 years followed for 10 years found that individuals with hypoalbuminemia had a 2.7-fold higher mortality risk after adjustment for confounders, and that overall mortality decreased by 16% per 1 g/L increase in albumin." (PMID 41431585, 2025). "Furthermore, hypoalbuminemia has been shown to be associated with infection severity and sepsis development, particularly in critically ill patients, as systemic inflammation leads to increased capillary permeability and alterations in albumin metabolism." (PMID 40005472, 2025). "Finally, although hypoalbuminemia has been demonstrated to be a risk factor of polymyxin AKI, hypoalbuminemia correction by administering exogenous albumin with the hope of preventing or mitigating nephrotoxicity has no clinical data so far and it is not advisable." (PMID 41301633, 2025). "Expanded checklist-based risk stratification, including:BMI ≥25 kg/m2, hypoalbuminemia, creatinine clearance <60 mL/min, diarrhea, and drug interactions.Patients with ≥3 risk factors considered high-risk; recommends pre-infusion optimization (e.g., albumin correction, fluid drainage)." (PMID 41278262, 2025). "However, it is uncertain whether this risk is caused directly by albumin administration or hypoalbuminemia." (PMID 39679665, 2024). "Importantly, our results highlight that clinical risk stratification strategies that only focus on hypoalbuminemia may insufficiently consider the increased risk of patients with low-normal albumin levels (35.0–39.9 g/L)." (PMID 38794724, 2024). "Furthermore, hypoalbuminemia is common in critically ill patients, and high levels of inflammation are often associated with low albumin levels, which may significantly affect the concentrations of highly protein-bound drugs." (PMID 39563441, 2024). "However, there is concern that, under such conditions (involving relatively high-permeability membranes), excessive albumin losses may occur, which are possibly associated with hypoalbuminemia, at least for some ESRD-patient categories." (PMID 38238597, 2024). "In general, post-treatment hypoalbuminemia can be caused by decreased protein intake, decreased production in the liver due to hepatic failure or response to systemic inflammation, or increased loss of albumin, such as in protein-losing enteropathy and nephropathy." (PMID 38595652, 2024). "In addition, electrolytes and nutrients bound to transfused albumin may help correct deficiencies resulting from hypoalbuminemia." (PMID 38528491, 2024). "According to previous studies, hypoalbuminemia is closely related to the occurrence of a variety of postoperative morbidities (such as systemic infection), suggesting that severe albumin loss may be a predictor of the occurrence of postoperative complications in patients with BTC." (PMID 38375202, 2023).
Hypoalbuminemia (continued). "While multivariable analysis confirmed that azotemia and hypoalbuminemia were independent risk factors for death before 12 months, response to therapy remained positively associated with 12‐month survival in the subset of dogs with less severe disease (ie, with normal creatinine and albumin)." (PMID 37815154, 2023). "Our multiple regression analysis showed a significant inverse correlation between albumin levels and COVID-19 pneumonia, suggesting that edema related to vascular permeability associated with hypoalbuminemia may contribute to the lesion extent of COVID-19 pneumonia on chest CT." (PMID 36653462, 2023). "In addition, hypoalbuminemia has been associated with an intolerance to enteral feeding due to mucosal interstitial edema, so patients with albumin infusions had better tolerance to enteral feeding, leading to a higher daily caloric intake, which also contributes to disease recovery in SAP patients." (PMID 37277756, 2023). "TNF-α could selectively inhibit the gene expression of albumin, causing hypoalbuminemia." (PMID 36157419, 2022). "It should be noted that hypoalbuminemia may not only be associated with abnormal liver function and diminished albumin synthesis in inflammation but may also be a consequence of a high clearance of damaged and oxidized albumin." (PMID 36077496, 2022). "Moreover, albumin can also maintain the integrity and function of the proximal tubule cells to exhibit the renal protection function in sepsis, and it is reported that hypoalbuminemia was a risk factor for renal failure." (PMID 35495750, 2022). "The persistent association between adverse clinical outcomes and hypoalbuminemia in a variety of clinical contexts suggest that the preoperative assessment of serum albumin concentration may be a robust and clinically useful predictor of adverse surgical outcomes." (PMID 36362771, 2022). "Hypoalbuminemia is associated with AN inflammatory response in critical illness; this due to the cytokines and chemokines released induce an increase in capillary leakage, altering the distribution of albumin between intravascular and extravascular compartments." (PMID 34620977, 2021). "Liver cirrhosis may cause hypoalbuminemia because albumin is synthesized exclusively in the liver." (PMID 34198972, 2021). "Additionally, albumin has the physiological properties as an anti-oxidant and drug transporter, and therefore, hypoalbuminemia could cause the insufficiency of these functions, leading to poor postoperative outcomes." (PMID 33685425, 2021). "Hypoalbuminemia is associated with inappropriate antimicrobial treatment and may be implicated by contributing to patient-related risk factors and other mechanisms relating to the pharmacokinetic and pharmacodynamic roles of albumin." (PMID 33925831, 2021). "However, whether albumin is only a marker or there is a cause-effect relationship between hypoalbuminemia and disease severity and mortality should be further evaluated." (PMID 34921151, 2021). "Therefore, this study was conducted to assess the association of hypoalbuminemia, reversal of albumin-to-globulin ratio and morbidity outcome in hospitalized LF-infected patients in a dedicated treatment center at Owo Local Government Area of Ondo State, south-western Nigeria." (PMID 33312698, 2020). "Therefore, hypoalbuminemia may be an independent risk factor to evaluate poor prognosis of severely patients with COVID-19, especially when albumin levels were below 29.6 g/L." (PMID 33041508, 2020). "Since for the studied patients, the hypoalbuminemia is associated with the presence of sepsis, the increased volume of distribution in patients with sepsis (with low albumin concertation) might be caused by other sepsis-related mechanism, like the increased capillary permeability." (PMID 32301057, 2020). "We hypothesized that hypoalbuminemia might result from albumin loss across the dialyzer." (PMID 31660886, 2019).
Hypoalbuminemia (continued). "However, we cannot conclusively distinguish between cause and effect of hypoalbuminemia and complications, it may be hypothesized that albumin serum levels were inadequately corrected." (PMID 30459814, 2018). "Quantification of albumin loss by direct analysis of the dialysate, together with analysis of markers of hepatic synthesis, may be a next step to guide dialysis choice avoiding hypoalbuminemia." (PMID 29986663, 2018). "Additionally, there has been reported that in patients with chronic diseases (e.g., congestive heart failure, liver cirrhosis and malignancy), in whom hypoalbuminemia resulting from decreased hepatic production of albumin is frequently the cause of pleural effusion." (PMID 27287396, 2016). "Some studies have shown that hypoalbuminemia in patients undergoing hemodialysis is unfavourable prognostic factor associated with the development of coronary heart disease and also that the level of albumin in plasma has a significant effect on the survival in hemodialysis patients." (PMID 27127544, 2016). "Therefore, in view of our surgical ICU (SICU) population (mostly surgical sepsis), the present retrospective study aimed to investigate the risk factors for developing hypoalbuminemia, as well as the effects of different albumin levels on the prognosis of surgical septic patients." (PMID 26557421, 2015). "The relationship between hypoalbuminemia and the risk of developing septic renal failure has been investigated in a meta-analysis of clinical observational studies describing the relationship between serum albumin and the incidence of acute kidney injury (AKI) using multivariate analysis." (PMID 26136776, 2015). "Several studies have reported a strong association between hypoalbuminemia and morbidity and mortality rates in HD patients, suggesting that nutritional interventions that maintain or increase serum albumin to normal levels may be associated with improved long-term survival." (PMID 24967248, 2013). "Background/Objectives: Hypoalbuminaemia is a consistent predictor of mortality in sepsis; however, the temporal dynamics of albumin decline and its relationship with fluid exposure and early norepinephrine therapy remain incompletely characterised." (PMID 42122937, 2026). "After PSM, the hypoalbuminemia group had a significantly higher incidence of PPCs compared to the normal albumin group (P < 0.05)." (PMID 42299149, 2026). "Laboratory tests revealed significant proteinuria (24-h urinary protein, 6.11 g), hypoalbuminemia (serum albumin, 20.07 g/L), and impaired renal function (serum creatinine, 129.90 μmol/L; eGFR, 45.2 mL/min/1.73 m2)." (PMID 42063792, 2026). "This Bf pool can increase substantially under conditions that reduce binding affinity to albumin, such as drug displacers, elevated free fatty acid levels, acidosis, or hypoalbuminaemia in newborns." (PMID 41144788, 2026). "Patients were stratified into a hypoalbuminemia group (<35 g/L) and a normal albumin group (≥35 g/L) based on the lowest albumin concentration in the 48 h before operation." (PMID 42299149, 2026). "In total, 67.9% of patients (n = 1400) were considered to have hypoalbuminemia defined as an albumin level < 35 g/L." (PMID 41452958, 2026). "Patients with hypoalbuminaemia were 1.8 times more likely to die, with a one-year survival rate of only 66% compared to 83% in those with a normal albumin level." (PMID 41596354, 2026). "A severe subgroup was defined by a relative albumin fraction <40% to evaluate patterns in marked hypoalbuminaemia." (PMID 41898363, 2026). "Laboratory findings showed acute kidney injury (creatinine 2.5 mg/dL), hypoalbuminemia (albumin 2.4 g/dl), and nephrotic range proteinuria (urine protein/creatinine = 17 gm/gm)." (PMID 41769596, 2026). "Within this state, IL-6 suppresses hepatic albumin synthesis while promoting acute-phase protein production, and increased vascular permeability exacerbates hypoalbuminemia." (PMID 41601745, 2026).
Hypoalbuminemia (continued). "Patients were divided into two groups based on preoperative albumin levels: hypoalbuminemia (< 3.5 g/dL) and normal (≥ 3.5 g/dL)." (PMID 41840567, 2026). "Albumin is a recognized biomarker of critical illness, and hypoalbuminemia indicates poor prognosis in systemic inflammation, while ALP levels correlate with conventional inflammatory markers." (PMID 41601745, 2026). "By year 10, survival had declined to 23.8% in the low-albumin group compared with 56.6% among patients with albumin ≥ 3.5 g/dL, highlighting the long-term prognostic significance of baseline hypoalbuminemia." (PMID 41517580, 2026). "Ileal involvement and hypoalbuminemia (median albumin 28.02 g/L, IQR 22.1-33.0) were present in all patients." (PMID 41899356, 2026). "The presence of hypoalbuminemia, defined as low serum albumin levels, further complicates this scenario, as it has been shown to independently predict acute kidney injury (AKI) and mortality within the intensive care population." (PMID 41401154, 2025). "Falsely low values for serum magnesium concentration occur with hypoalbuminemia, since approximately 30% of magnesium is bound to circulating albumin or if the sample is contaminated with potassium ethylenediaminetetraacetic acid (kEDTA)." (PMID 40868117, 2025). "Our study also observed a significant decline in albumin levels from admission to outcome, underscoring the critical role of hypoalbuminemia in disease progression." (PMID 40649865, 2025). "Persistent edema prompted albumin administration (day 4) to address hypoalbuminemia and low-dose dopamine for administration renal perfusion." (PMID 40922353, 2025). "In our study, patients with severe hypoalbuminemia and significant chronic comorbidities received albumin replacement therapy, whereas those with mild hypoalbuminemia were managed with nutritional support." (PMID 41303773, 2025). "Administration of human serum albumin (HSA) solutions is an established treatment for hypoalbuminemia in dogs." (PMID 41158946, 2025). "Considering the potential impact of hypoalbuminemia, albumin replacement therapy emerges as a prospective treatment for pregnant women with preeclampsia." (PMID 39857389, 2025). "Hypoalbuminemia treatment typically involves the administration of 5%, 20%, or 25% albumin, which are sterilized at 60.5 °C for 10–11 h to mitigate the risk of viral infection." (PMID 40699702, 2025). "and ertapenem at a dose of 15 mg/kg b.w. in states of normoalbuminemia, plasmapheresis-induced hypoalbuminemia (26.1 g/L) and hyperalbuminemia induced by administration of 25% albumin solution (35.8 g/L)." (PMID 40051558, 2025). "Hypoalbuminemia, mostly defined as preoperative albumin <3.5 g/dL, has been proved as an independent predictor of poor perioperative outcomes in women who have undergone open surgery for gynecologic malignancies." (PMID 39941787, 2025). "The patient’s urine albumin quantification was >3.5 g/24 h, accompanied by hyperlipidemia, hypoalbuminemia, and symmetrical pitting edema in both lower extremities, all of which are characteristic features of nephrotic syndrome." (PMID 41030252, 2025). "On admission, about two-thirds of patients had normal albumin (3.5–4.6 g/dL), and roughly one-quarter presented with hypoalbuminemia (<3.5 g/dL)." (PMID 41226896, 2025). "The observed hypoalbuminemia further reflects systemic inflammation and catabolic stress, as albumin synthesis is downregulated during acute-phase responses." (PMID 40539153, 2025). "A limitation of the study was that the difference in albumin concentration was too small when comparing normo and hypoalbuminemia." (PMID 40051558, 2025). "This research explores the safety of human albumin infusion in treating heart failure patients with hypoalbuminemia, despite limited clinical data on its use with diuretic therapy." (PMID 40279952, 2025). "In our case, the patient required repeated albumin infusion, which reflected the severity of hypoalbuminemia." (PMID 41209104, 2025).
Hypoalbuminemia (continued). "After infancy, normal serum albumin levels rise to 3.4–5.6 g/dL, and values below 3.3 g/dL at any age are considered hypoalbuminemia." (PMID 40567610, 2025). "Inflammation increases capillary permeability, leading to the escape of serum albumin, while acute disease results in greater albumin degradation, leading to a state of hypoalbuminemia." (PMID 40428888, 2025). "By ICU discharge, albumin shifted upward: extreme hyperalbuminemia (≥5.5 g dL−1) 62.6%, hyperalbuminemia 15.8%, normoalbuminemia 20.4%, and hypoalbuminemia ≤ 1.3%." (PMID 41226896, 2025). "Laboratory analyses also include determining the level of serum albumin to assess the degree of hypoalbuminemia." (PMID 40868160, 2025). "The mean serum albumin level across the cohort was 2.6 g/dL (±0.5), and 87.2% of patients (360/413) had albumin levels below the normal reference range (<3.5 g/dL), indicating a high prevalence of hypoalbuminemia at presentation." (PMID 40648856, 2025). "The albumin level can also serve as a prognostic marker of hypoalbuminemia; it can reflect levels of physiological stress due to inflammation resulting from disease or trauma." (PMID 40649163, 2025). "The levels of serum albumin and globulin influence inflammation and immune function, with hypoalbuminemia and hyperglobulinemia commonly considered markers of chronic inflammation in cancer patients." (PMID 40308604, 2025). "In individuals receiving warfarin, the uric acid/albumin ratio, hypoalbuminemia, elevated urea, and supratherapeutic INR were key predictors." (PMID 41227038, 2025). "This study conducted subgroup analyses by albumin levels to examine clinical outcomes in patients with hypoalbuminemia, who were divided into the following subgroups: 0–1, 1–2, 2–3, and 3–3.5 g/dL." (PMID 40649163, 2025). "Albumin is the most abundant protein in human plasma, and a level below 35 g/L is defined as hypoalbuminemia." (PMID 41200138, 2025). "Postoperative morbidity was higher in the hypoalbuminemia group, with wound dehiscence occurring in 11.9% of patients compared to 2.5% in the normal albumin group, a statistically significant difference (p=0.018)." (PMID 40161084, 2025). "Blood values showing hyperproteinemia, hyperglobulinemia, and hypoalbuminemia, which resulted in a low albumin-to-globulin ratio, suggested feline infectious peritonitis in some cases." (PMID 40508970, 2025). "Recipients were categorized based on pretransplant albumin level as normal (≥4.0 g/dL, N = 222, 42%), mild hypoalbuminemia (≥3.5–<4.0 g/dL, N = 190, 36%), and moderate hypoalbuminemia (<3.5 g/dL, N = 120, 23%)." (PMID 39906535, 2025). "Although hypoalbuminemia is likely to be multi‐factorial, albumin levels have been suggested to be a more potent indicator of inflammation than of low nutritional status." (PMID 38477040, 2025). "Laboratory tests demonstrated nephrotic-range proteinuria (24 h UTP 12.80 g/d), severe hypoalbuminemia (serum albumin 19.30 g/L), and marked hyperlipidemia (triglycerides 4.56 mmol/L, total cholesterol 8.83 mmol/L, and LDL-C 5.73 mmol/L)." (PMID 41244787, 2025). "Given that hypoalbuminemia is common in HF, the albumin-corrected anion gap (ACAG) is particularly relevant for HF patients, as it adjusts for hypoalbuminemia and more accurately reflects the burden of unmeasured anions and acid-base disturbances." (PMID 40951817, 2025). "Hypoalbuminemia reflects the redistribution of albumin into the interstitium, increased degradation, and shortened half-life secondary to inflammatory signaling, rather than a simple deficit amenable to replacement." (PMID 41228270, 2025). "Demographics of patients with normal albumin (≥35 g/L) versus those with hypoalbuminemia (<35 g/L) postoperative hip fracture in elderly." (PMID 41488107, 2025). "Length of hospital stay was evaluated in two studies, one of which utilized a continuous albumin level and while the other utilized discrete hypoalbuminemia as defined by albumin <3.5 g/dL." (PMID 40103850, 2025).